HIF1A (hypoxia inducible factor 1 subunit alpha)
Diseases named in the same sentence as HIF1A in open-access papers (continued):
Sharing a sentence is not in itself a finding about the gene and the disease.
tumor (continued). "HIF1A mRNA was decreased in tumor tissue compared to healthy tissue but without statistical significance." (PMID 40332447, 2025). "The expression analysis showed that ESR1 had no expression difference between normal and tumor groups; BCL2 expression was lower in tumor group (P < 0.001); while AKT1, CCND1, and HIF1A expressions were higher in tumor group compared with those in normal group (all P < 0.001)." (PMID 40552073, 2025). "Consequently, the expression of HIF-1α target genes is inhibited by PPA2, which subsequently inhibits tumor cells’ glycolytic, survival and metastatic capabilities." (PMID 40164945, 2025). "Our studies have established that the WWOX/HIF1A ratio is a key regulatory axis in cancer biology, orchestrating cellular differentiation, metabolic reprogramming, invasiveness, EMT regulation, angiogenesis, and immune evasion in multiple tumour types." (PMID 41007296, 2025). "We conducted a correlation analysis of the expression of PAX6 and HIF-1α in each tumor sample and found that there was a negative correlation between the two." (PMID 41154694, 2025). "EPOR levels in tumor tissue were reduced compared to surrounding healthy tissue in the absence of HIF1A." (PMID 40332447, 2025). "However the high expression of HIF-1α increases the expression of VEGF and other genes, tumor neovascularization, local tumor microcirculation perfusion, and dilutes tumor local acidity to some extent." (PMID 40444079, 2025). "Notably, HIF‐1α activation under hypoxic conditions exacerbates IGF signaling, facilitating tumor growth and invasion." (PMID 40060195, 2025). "This can be achieved by using siRNA-loaded TAT-chitosan-SPION nanoparticles, which significantly reduced the expression levels of HIF-1α and CD73 in tumor cells (<25% compared to untreated cells), leading to decreased migration, proliferation, and tumor growth." (PMID 40872479, 2025). "Immune infiltration analysis also suggested that the increase of HIF1A in PTC may induce the dedifferentiation of tumor cells and promote the tumor deterioration by inhibiting the activity of NK cells." (PMID 40552073, 2025). "The HIF-1α/Stearoyl-CoA Desaturase 1 (SCD1) axis-mediated accumulation of lipid droplets and HVEM-regulated aerobic glycolytic reprogramming in T cells further highlight the complex, multidimensional potential of metabolic interventions in cold tumor therapy." (PMID 41050070, 2025). "In addition, hypoxia-inducible factor-1 alpha (HIF-1α) inhibitors can organize TAMs to M2 polarization, but send M1 polarization, promote its inhibiting tumor angiogenesis, and promote its maturity." (PMID 40821116, 2025). "Furthermore, locoregional therapy modifies the tumor microenvironment, for instance, by promoting the release of VEGF and hypoxia-inducible factor-1α (HIF-1α), which further potentiates the effect of targeted agents." (PMID 41347074, 2025). "Comparing the parental tumor core and margin, distinct molecular profiles were revealed, with the tumor margin showing elevated expression of markers such as CD44 and HIF1A, consistency with stemness, hypoxic adaptation, and metabolic reprogramming at the invasive front." (PMID 40431665, 2025). "Taken together these data suggest a tumor suppressor role for HIF-1α, whereby stabilization of HIF-1α actively limits aspartate biosynthesis by suppressing cytosolic GOT1 and mitochondrial GOT2, and further reduces glutamine incorporation into TCA cycle intermediates." (PMID 39914740, 2025). "Furthermore, protein expression levels in the tumor tissue revealed that miR-6126 inhibits the expression of Warburg effect-related signaling proteins such as GRP78, HIF1α, GLUT1, and LDHA but induces PTEN expression." (PMID 40959569, 2025). "Furthermore, lidocaine appears to interfere with the activation of hypoxia-inducible factor 1-alpha (HIF-1α), which regulates genes involved in cellular responses to hypoxia, angiogenesis, and tumour dissemination." (PMID 40507646, 2025).
tumor (continued). "In addition, under hypoxic conditions, the effects of hBMSC-MVs on the progression of U2OS cells and tumor growth are related to the PI3K/AKT and HIF-1α pathways." (PMID 41035670, 2025). "This suggests that hypoxia-induced GRPR signalling may cooperate with HIF-1α–regulated survival pathways, further supporting GRPR as a critical mediator of tumour adaptation under low-oxygen conditions." (PMID 41226822, 2025). "Furthermore, nanoformulationshave been proposed to efficiently control relevant pro-angiogenicpathways such as VEGF, Tie2/Angiopoietin-1, HIF-1α/HIF-2α,and TGF-β, providing powerful approaches to block tumor growthand metastasis." (PMID 40184281, 2025). "Many literature reviews have revealed that the HIF-1α/VEGF signaling pathway has a unique and important function in tumor angiogenesis, but triggering CLG also requires angiogenesis to increase the alveolar number and alveolar density, thereby enhancing residual lung function." (PMID 40601668, 2025). "HIF-1α targets VEGF, a key angiogenic factor in tumor progression." (PMID 40100307, 2025). "In addition, flavonols can inhibit tumor angiogenesis by downregulating VEGF, HIF-1α, and other angiogenic factors, starving tumors of blood supply." (PMID 40808836, 2025). "In addition, gambogic acid inhibited HIF-1α and VEGF, leading to tumor vascular normalization, reduced hypoxia stress, and improved immune cell infiltration." (PMID 41019982, 2025). "Additionally, MIF sustains tumor cell viability through the AKT survival pathway via an autocrine feedback loop, and promotes angiogenesis through HIF1α-dependent signaling or the NFκB–IL8–VEGF axis, as reported in several tumor models." (PMID 40835826, 2025). "Firstly, under moderate hypoxia, prolyl hydroxylase activity is partially maintained, allowing a proportion of HIF-1α molecules to undergo hydroxylation and subsequent recognition by VHL, as evidenced by detectable hydroxylated HIF-1α in hypoxic tumor regions and moderately hypoxic cells." (PMID 41446875, 2025). "Additionally, hypoxia promotes the expression of HIF1A, further stimulating EMT and consequently enhancing tumor invasion and resistance to chemotherapy." (PMID 40575382, 2025). "Mechanistically, DLEU1 may serve as a cofactor and activate HIF-1α-mediated transcription of CKAP2, thereby activating the ERK and STAT3 signaling pathways to promote tumor growth." (PMID 40004471, 2025). "Histological analysis (H&E, TUNEL, and HIF-1α staining) revealed increased TUNEL expression and decreased HIF-1α expression in the PTL@GC group, indicating that the film inhibited tumor growth and alleviated the hypoxic microenvironment." (PMID 40358287, 2025). "This difference may be attributed to the intrinsic instability and rapid degradation of HIF-1α, suggesting the possibility that long-acting iron chelators may robustly induce HIF-1α in tumors, thereby exerting a tumor-suppressive effect." (PMID 40343532, 2025). "Molecular endogenous markers such as HIF-1α, carbonic anhydrase IX (CAIX), glucose transporters 1/3 (GLUT-1/3), vascular endothelial growth factor (VEGF), and monocarboxylate transporter 4 (MCT-1) also play a role in the assessment of tumor hypoxia." (PMID 40724929, 2025). "Notably, traditional Chinese medicine YiFeiSanjieWan mitigates CRF symptoms by inhibiting the Stat3/HIF-1α/BNIP3 signaling pathway, which is induced by aberrantly activated tumor-related inflammation." (PMID 41018226, 2025). "This study found that SH administration could inhibit HIF-1α and VEGF protein expression, preventing tumor angiogenesis." (PMID 41444284, 2025). "HIF-1α further enhances the expression of glycolytic enzymes and glucose transporters (e.g., GLUT1), increasing glycolytic flux to meet the energy demands of both tumor and immune cells." (PMID 41200171, 2025).
tumor (continued). "Notably, HIF-1α has been shown to bind to the promoter region of the HILPDA gene to activate transcription of HILPDA, as well as promote tumor proliferation, metastasis, and drug resistance." (PMID 39920992, 2025). "Based on bioinformatics analysis and literature review, we hypothesize that L-2-HG may promote HIF1A by regulating of histone lactylation modification and facilitate RCC brain metastasis by affecting tumor cell iron death." (PMID 41198650, 2025). "In particular, STAT3 has been shown to physically interact with HIF-1α and co-recruit p300/CREB-binding protein (p300/CBP) and RNA-Polymerase II to the vascular endothelial growth factor (VEGFA) promoter in hypoxic tumor cells, thereby reinforcing transcription of angiogenic genes." (PMID 40867898, 2025). "Importantly, HIF-1α can interact with the Wnt/β-catenin signaling pathway through the transcriptional upregulation of calreticulin (CALR), thereby enhancing tumor development." (PMID 41373022, 2025). "In summary, miRNAs can target and regulate TGFBR2, HIF1α, and VEGFA to inhibit tumor angiogenesis." (PMID 39857292, 2025). "In GBM, our data indicate low WWOX/HIF1A ratios activate multiple proliferative and survival pathways regulated by HIF1A and its cofactors, including Wnt, TGF-β, AP2α, and AP2γ, collectively driving tumour progression and resistance to apoptosis." (PMID 41007296, 2025). "Inhibition of HIF-1α reduces VEGF expression and suppresses tumor cell proliferation and invasion." (PMID 41583457, 2025). "Among cases with high PD-L1 expression, 95.8% exhibited HIF-1α positivity in the tumor microenvironment, while 4.2% were negative." (PMID 39996842, 2025). "Intermittent hypoxia activates the NF-κB/HIF-1α pathway, increasing pro-inflammatory mediators like COX-2, CCL2, CXCL1, PGE2, and CSF1, these mediators recruit monocytes and neutrophils to the tumor microenvironment (TME), differentiating into TAMs and Tumor-Associated Neutrophils (TAN)." (PMID 41357522, 2025). "The results of network pharmacology and molecular docking analyses suggested that SSA may interact with BCL2, ESR1, HIF1A, and STAT3 as well as PI3K/AKT signalling pathways and inhibit tumour growth by promoting apoptosis." (PMID 39995416, 2025). "Tumor-derived factors such as TGF-β and HIF-1α drive this metabolic reprogramming in CAFs." (PMID 41441395, 2025). "HIF1A upregulates USP51 expression under hypoxic conditions, while USP51 stabilizes HIF1A via deubiquitination, thereby maintaining its activity and supporting the proliferative and migratory capacities of tumor cells." (PMID 39995416, 2025). "Although HIF-1α exhibits cancer-aggressive effects and impairs therapyresponse in various cancers, including HNSCC, research indicates that HIF-2α playsessential roles with distinct phenotypic characteristics in tumor development." (PMID 40636217, 2025). "Moreover, TRAP1 stabilizes HIF1α via SDH inhibition, promoting the downstream genes that enhance angiogenesis and nutrient supply in proliferating tumor cells." (PMID 41226319, 2025). "Experiments conducted on murine-derived tumour models and cell lines identified HIF-1α mRNA transcripts as the target of miR-17–92 clusters, miR-20b and miR-199a miRNA molecules that thereby regulate the protein abundance of HIF-1α." (PMID 41361850, 2025). "HIF-1α was shown to also enhance expression of collagen-modifying enzyme Procollagen-Lysine,2-Oxoglutarate 5-Dioxygenase 2 (PLOD2), facilitating a collagen structure conducive to tumor cell migration and lung colonization." (PMID 41174561, 2025). "Moreover, HIF-1α can interact with other oncogenic pathways, such as PI3K/Akt and STAT3, to form feed-forward loops that enhance tumor aggressiveness and therapy resistance." (PMID 40867898, 2025). "In our study, we isolated the total proteins from the tumor and healthy tissue samples to investigate the factors responsible for the lower expression of HIF1A without separating proteins from the nucleus and cytoplasm." (PMID 40332447, 2025).
tumor (continued). "Collectively, these findings reveal that TRP channels intersect with central pathways such as HIF-1α, AMPK, PI3K/AKT, NRF2, and mitochondrial signaling, underscoring their pivotal role in supporting tumor metabolism, redox balance, and therapeutic responsiveness." (PMID 40813985, 2025). "HIF-1α is a key transcriptional factor in the cellular response to hypoxia, which can induce the production of VEGF and other angiogenic factors, thereby enhancing tumor angiogenesis and increasing the tumor’s invasiveness and metastatic capacity." (PMID 40129974, 2025). "Hypoxic tumor cores exhibit glycolytic dependency mediated by HIF-1α stabilization, targetable through HIF-1α inhibitors (adamantane derivatives, MO-2097, NLG207, NB-5-MT), combined with glycolytic enzyme blockade (HK2 inhibitor PF-04691502, LDHA inhibitor FX-11)." (PMID 40725147, 2025). "Additionally, the activation state of HIF-1α stabilization and SUCNR1 signaling in our tumor model needs direct examination." (PMID 41568043, 2025). "Additionally, MYCN has been demonstrated to interact with additional oncogenic factors, including hypoxia-inducible factor 1-alpha (HIF-1α), thereby enhancing its influence on tumor progression." (PMID 40429864, 2025). "Therefore, the regulation of the HIF-1α/MMP and HIF-1α/ADAM signaling pathways is of great importance for the clinical prognosis of tumor patients." (PMID 40563539, 2025). "HIF-1α activation not only regulates the expression of glycolysis-related enzymes, such as hexokinase and lactate dehydrogenase but also enhances the expression of glucose transporters (GLUT), thereby increasing glucose uptake by tumor cells." (PMID 41190142, 2025). "For example, single-cell technology can reveal that certain tumor subpopulations are more dependent on key pathways related to glucose metabolism (such as PI3K/AKT/mTOR and HIF-1α), which may provide a basis for targeted therapy." (PMID 39980550, 2025). "Furthermore, this glycolytic phenotype is further promoted by hypoxia-inducible factor 1-alpha (HIF-1α) activation in low-oxygen conditions, which strengthens the ability of cancer cells to survive in hypoxic tumor cores." (PMID 40277923, 2025). "Although limited data exists, HIF1α has been shown to induce the expression of CRP and other pentraxins in tumor cells and neurons, while CRP has been shown to stabilize HIF1α expression in adipose-derived stem cells as well as induce angiogenic activity in endothelial cells." (PMID 41614767, 2025). "HIF-1α and ER would be highly active in AHR-high ER+ tumours." (PMID 40646277, 2025). "HIF-1α serves as the molecular linchpin, simultaneously upregulating VEGF while activating PI3K/Akt/mTOR and MAPK signaling cascades, thereby creating a feedforward loop that sustains tumor vascularization and progression." (PMID 40620671, 2025). "This may reflect biological effects of transarterial chemoembolisation, which can upregulate HIF-1α, VEGF and regulators of epithelial–mesenchymal transition, thereby exacerbating hypoxia and reinforcing immunosuppression within the tumour microenvironment." (PMID 41415570, 2025). "PFS was significantly lower in HIF-1α tumor-positive cases compared to HIF-1α tumor negative ones (p = 0.030)." (PMID 39857068, 2025). "Therefore, HIF-1α-mediated ECM remodeling is a critical feature that alters the overall TME, making it more prone to tumor formation, invasion, and metastasis." (PMID 38542288, 2024). "Succinate has been identified as having many pro-oncogenic roles, including HIF1α stabilisation, alteration of the tumour microenvironment, promotion of metastatic potential via enhanced EMT, suppression of anti-tumour immune responses and the activation of pro-inflammatory signalling pathways." (PMID 39025852, 2024).
tumor (continued). "FOXA1 and FOXA2 regulate the hypoxic transcriptional program inversely when PCa is in a hypoxic tumor microenvironment, and which of FOXA1 and FOXA2 tends to regulate HIF1A may depend on the high or low expression of FOXA1 and FOXA2 in the PCa phenotype." (PMID 38605023, 2024). "Moreover, HIF-1α is increased in oral squamous cell carcinoma (OSCC), controlling aggressiveness and tumor size." (PMID 38544822, 2024). "Knockout of HIF-1a led to improved survival of GBM-bearing mice due to a lack of Treg infiltration of the tumor." (PMID 38786032, 2024). "The stability of HIF1α is greatly increased in hypoxia, and HIF induces transcription by binding to hypoxia-responsive elements (HREs) in the promoter of target genes, including microRNAs, to promote tumor malignancy." (PMID 38485986, 2024). "In a hypoxic TME, HIF-1α activation stimulates the differentiation of bone marrow-derived myeloid progenitor cells into MDSCs, which then migrate to the TME under the influence of various tumor-secreted chemokines, enhancing immunosuppression in the TME." (PMID 39227970, 2024). "Furthermore, HIF1A can overexpress LDH-A (lactate dehydrogenase) which thus facilitates the accumulation of lactate in the tumor microenvironment and promotes tumor invasiveness, drug resistance, and immune escape of tumor cells." (PMID 38462658, 2024). "HAMLET sensitivity was further modified by the glycolytic state of tumor cells as glucose deprivation sensitized tumor cells to HAMLET-induced cell death and in the shRNA screen, hexokinase 1 (HK1), 6-phosphofructo-2-kinase/fructose-2,6-biphosphatase 1 and HIF1α, modified HAMLET sensitivity." (PMID 38360830, 2024). "In particular, it has been demonstrated that overexpression of CLOCK enhances the expression of genes related to angiogenesis, including vascular endothelial growth factor (VEGF), hypoxia-inducible factor 1-alpha, (HIF1α), and basic helix-loop-helix (BMAL1), which is a tumor suppressor." (PMID 38892035, 2024). "Moreover, tumor-derived succinate triggers the reprogramming of peritoneal macrophages and enhances their migration via the succinate receptor 1 (SUCNR1)/PI3K/HIF-1α signaling pathway, ultimately increasing Arg1 expression and promoting arginine metabolism." (PMID 38185636, 2024). "At the same time, Vegf expression increased only in the tumor tissue of the SH animals relative to the control, and no changes in Hif1a, Epas1, or Hif3a expression were noted either in the tumor tissues or in the peritumoral area." (PMID 39063041, 2024). "Finally, we evaluated the correlation between the protein expression of IDH1 and HIF1a and the IC50 of Scu in different tumor cell lines under hypoxia." (PMID 38622131, 2024). "By sustaining glycolysis, HIF1α maintains [acetyl-CoA], IFN-γ induction, tumor-killing ability of hypoxic T cells, and tumor responses to ICB, identifying loss of HIF1α as a major T cell-intrinsic mechanism of ICB resistance, which can be overcome by acetate supplementation." (PMID 39477954, 2024). "Additionally, hypoxic exosomes derived from pancreatic cancer cells can induce macrophages to adopt an M2 phenotype in a manner dependent on HIF-1α or HIF-2α, further promoting EMT in tumor cells." (PMID 39430253, 2024). "Lactate can stabilize HIF-1α and induce the expression of M2 genes such as Arg-1, Fizz-1, Mgl-1, VEGF, and PPAR-γ, thereby inducing TAM polarize to an M2 immunosuppressive phenotype and promoting tumor growth, metastasis, and invasion." (PMID 38835758, 2024). "In this process, HIF-1α binds to the hypoxia-responsive element (HRE) within the VEGF promoter, forming an HIF-1α/HRE complex that directly upregulates VEGFR-1 expression in tumor cells." (PMID 39737184, 2024). "We further analysed the correlation between CXCL12, CD44v6, HIF1A, TGFBR2 and KRT7 expression in metastatic tumor tissues & exosomes with sex, age, habit, Tumor Differentiation grade, TNM stage, EGFR mutation status, AE1, Chromogranin, CDX2, CEA, CK20, TTF-1 & CK7." (PMID 38877052, 2024).